IFNG (interferon gamma)
Diseases named in the same sentence as IFNG in open-access papers (continued):
Sharing a sentence is not in itself a finding about the gene and the disease.
tumor (continued). "However, interferon gamma (IFN-γ) facilitates tumor initiation and increases tumor fitness." (PMID 32728097, 2020). "However, mutational load did not correlate in all tumor types with IFNγ signature or T cell infiltration." (PMID 33228231, 2020). "Importantly, this suggests that the higher observed proportion of IFNγ and IFNγ-expressing cells in combination-treated tumors from our study are indicative of not only reduced tumor growth in mice but is more likely to be clinically translatable to patient outcomes." (PMID 33247183, 2020). "Interestingly, tumor-infiltrating immune cells might have increased sensitivity to IFNG and upregulate PD-L1 to suppress a preexisting T-cell response prior to treatment." (PMID 33299118, 2020). "The authors found that the clonotypes of tumor-infiltrating CD8+ T cells after anti-PD-1 therapy were phenotypically enriched with activation/dysfunction-associated markers including TH1-associated cytokines (TNFα, IFNγ), checkpoint receptors (PD-1, TIM-3, LAG-3), and CD103." (PMID 32707692, 2020). "Thus, identifying tumor-specific CTLs solely using IFNγ-based techniques might overlook a large fraction of antigen-specific T cells and could generate unexpected biases in analyses, especially during ex vivo evaluation of anti-tumor responses from TILs." (PMID 32194559, 2020). "Therefore, the production of IFNg may act as a major inductor of NK cell cytotoxicity towards tumor target cells." (PMID 30616690, 2019). "Furthermore, we found that lycopene could synergistically function with anti-PD-1 to improve IFNγ expression of CD8+ cells infiltrated in the tumor tissues." (PMID 30948928, 2019). "Activated NK cells can stimulate the activity of other immune processes through their release of cytokines (such as IFNγ), providing a link to initiate subsequent immune responses to attack target tumors, which may have resulted in a tumor response in this patient." (PMID 31412935, 2019). "Thus, CD4+ and CD8+ T cells frequently infiltrate GBC tumor tissues, may lead to IFNγ stimulation of tumor cells and thereby, to activation of tumor suppressive STAT1 signaling." (PMID 30886199, 2019). "Moreover, the production of IFNγ favoring a Th1 cellular response usually produces cytotoxic macrophages and effector cytotoxic T cells that would suppose a potential favorable response against tumor development." (PMID 31450563, 2019). "Interestingly, the results showed that the IFNγ, TNFα, and IL-6 levels in the serum of the CAR-147 macrophage group were decreased compared with that of the control group, while the IL-12 and IFNγ levels were increased in tumour tissue samples from the CAR-147 macrophage-treated mice." (PMID 31570753, 2019). "Moreover, the presence of CD8+ T cells and increased interferon-gamma (IFNγ) expression were shown to have a better prognostic value than the classic tumor node metastasis classification factor, whereas a T helper 17 (Th17) T-cell-dominated immune response was associated with a worse outcome." (PMID 31072360, 2019). "Furthermore, TNFα and IFNγ in combination induce tumor cell senesce mediated by CD4+ T cells (Th1)." (PMID 30833945, 2019). "These CD4+ ICOS+ T cells produced IFNγ and could recognize tumor antigens." (PMID 31192215, 2019). "Notably, release of IFNγ by NK cells in response to tumor cells that is reinforced by denosumab treatment not only may mediate direct antitumor effects but also stimulates subsequent adaptive immune responses." (PMID 30813611, 2019). "Thus, when retrieved from the tumor 12 days after their transfer, they presented a characteristic high surface expression of inhibitory receptors, diminished production of IFNγ and TNFα, and low cytolytic activity as well as the expression of the high-mobility group (HMG)-box TFs - TOX and TOX2." (PMID 31766350, 2019).
tumor (continued). "The expression of PD-L1 on tumor cells might be induced by the secretion of IFNγ via Janus kinase/signal transducer and activator of transcription 3 (JAK/STAT3) and the phosphatidylinositol 3-kinase (PI3K)/protein kinase B (Akt) signaling pathways, which has been shown in lung cancer." (PMID 31430935, 2019). "Interestingly, LFA-1 blockade and to a lesser extent ICAM-1 blockade caused a decrease in T cell IFNγ production in mixed tumor/T cell cultures but did not affect the level of T cell infiltration into the tumor." (PMID 31231358, 2019). "Furthermore, IFNγ (TME) activates the expression of CTLA-4 in the tumor microenvironment." (PMID 31192129, 2019). "To study whether this was linked to IL-27-signaling in macrophages, we generated BMDM from WT and IL27Rα KO mice and induced classical activation with LPS/IFNγ, alternative activation with IL-4, or directly co-cultured them with PyMT cells to induce tumor-like conditions." (PMID 31637217, 2019). "Additionally, CD8+ T cell production of IFNγ was similarly enhanced in primary tumor." (PMID 30898149, 2019). "Previous studies have suggested that IFNγ-expressing T cells could suppress tumor angiogenesis." (PMID 30373628, 2018). "Alternatively, tumor immunosuppression can be overcome by directly stimulating the immune system by the local administration of immunostimulant cytokines such as interleukin-12 (IL-12) and interferon-gamma (IFN-γ) which have been shown to be downregulated in the GBM microenvironment." (PMID 29755109, 2018). "This could be explained by the contribution of IFNγ to tumor evasion." (PMID 30039553, 2018). "However, ILC1s were not potent IFNγ producers and conversion of NK cells into ILC1s was associated with decreased anti-tumor activity." (PMID 30400618, 2018). "Furthermore, when activated human T cells were co-cultured with PD-L1 positive human tumor cells, PD1-Fc- OX40L was observed to concentrate within the immune synapse, which enhanced proliferation of T cells and production of IL-2, IFNγ and TNFα; leading to efficient killing of tumor cells." (PMID 30400822, 2018). "Hence, contrary to the common perception of PD-L1 expression as a biomarker of response to PD-1 blockade, PD-L1 expression is a biomarker of IFNγ-secreting tumor-reactive T cells in the tumor environment on which PD-1 blockade may act." (PMID 29876010, 2018). "Furthermore, when activated human T cells were co-cultured with PD-L1 positive human tumor cells, PD1-Fc-OX40L was observed to concentrate to the immune synapse, which enhanced proliferation of T cells and production of IL-2, IFNγ and TNFα, and led to efficient killing of tumor cells." (PMID 30563566, 2018). "We ran preliminary IgG arrays with sera harvested from animals used in the tumor challenge and in vitro experiments already presented, and these preliminary arrays were used to identify outlier antigens of interest for final IgG array experiments paired with IFNγ T cell assays." (PMID 29618380, 2018). "Moreover, B220+CD11c+NK1.1+ cells demonstrated anti‐metastatic tumour ability with IFNγ induction." (PMID 29930175, 2018). "Therefore, targeting the recruitment of proangiogenic monocytes with anti-angiogenic therapy combined with IFNγ immunotherapy, may be a more valuable strategy to improve anti-tumour therapy." (PMID 29367702, 2018). "For example, ASCs stably modified to express IFNγ promote significant antimelanoma effects as compared to recombinant IFNγ treatment alone, suggesting that the mode of delivery of an antitumor cytokine in the tumor microenvironment is critical to its effectiveness." (PMID 29181035, 2017). "Thus, JAK2 deficiency protected Ma-Mel-54a cells not only from anti-tumour IFNγ activity but also conserved their HLA class I-low phenotype that in turn might have hampered effective T-cell recognition of the tumour cells." (PMID 28561041, 2017).
tumor (continued). "In addition to immune suppression by MDSC and Treg-specific mechanisms, tumor-associated macrophages, fibroblasts, mast cells, B cells, and T cells themselves within solid tumors may become PDL1+ in response to IFNγ." (PMID 28938530, 2017). "Upon tumor antigen recognition T cells produce interferon gamma, which through the interferon gamma receptor leads to beneficial antitumor effects, such as increased antigen presentation, increased production of chemokines and direct tumor growth arrest and apoptosis." (PMID 29069824, 2017). "In addition, decreased production of IFNγ due to unknown humoral inhibiting factors released from the tumor has been reported." (PMID 29050291, 2017). "Indeed, compared to the first generation of CAR T cells, (i) CD28-CAR T cells secrete higher levels of interferon gamma (IFNγ); (ii) efficiently eradicate transforming growth factor beta (TGFβ) producing tumor cells; and (iii) suppress TGFβ inhibition of T cell expansion." (PMID 28496440, 2017). "The results showed clonal selection of loss-of-function mutations in JAK1 and JAK2 in two patients, which led to lack of response to interferon gamma, and a truncating mutation in the antigen-presenting protein B2M in another case, resulting in decreased immune cell recognition of tumor cells." (PMID 29234329, 2017). "Thus, it was hypothesized that IFNγ released from tumor-infiltrating T lymphocytes could activate the JAK/STAT signaling pathway in EBV (+) GC cells." (PMID 29259270, 2017). "Thus, proliferation of tumor cells independent of PTEN status was significantly reduced in the presence of IFNγ- and TNFα-activated astrocyte-CM compared to normal culture media or to CM from co-cultures of astrocytes with tumor cells (231BR/CTL and 231BR/PTEN: p < 0.001)." (PMID 28008153, 2017). "IFNγ can activate cytotoxic T cells and macrophages to kill tumor cells; meanwhile, persistent expression of IFNγ can induce expression of immune checkpoint molecules such as PD-L1 on tumor cells and antigen-presenting cells to diminish T cell antitumor activities." (PMID 28424760, 2017). "Importantly, the IFNγ-induced expression of IDO by tumor cell lines was inversely correlated with the expansion rate of T cells in the corresponding MLTC and directly associated with the capacity of a tumor cell line to inhibit activation of T cells." (PMID 28401257, 2017). "In conclusion, although further prospective longitudinal studies are required to explain the precise mechanism involved in decreased NKA in GC patients, our results suggest that NK cell activities for IFNγ production could be used as a supportive non-invasive tumor marker for GC." (PMID 29050291, 2017). "As CD4+ effector cells are not commonly the cytotoxic effector cells in an immune response, we hypothesized that the combination treatment induced M1 polarization of mononuclear cells in the tumor microenvironment, potentially recruited by IFNγ-secreting CD4+ cells." (PMID 27190629, 2016). "As both patients also showed a prominent infiltration of CD8+ T-cells to the tumor after treatment and a clear increase in the gene expression level of IFNγ in tumor, these findings suggest induction of dynamic adaptive changes in response to T-cell-derived IFNγ." (PMID 26981247, 2016). "Furthermore, when these poxvirus-based immunotherapy candidates were used in combination with CTLA-4 blockade, increased lymphocyte proliferation, IFNγ production, and T cell avidity resulted in tumor rejection through immune responses to self-antigens in tolerant mouse models." (PMID 26961085, 2016). "M1 macrophages can be activated by Th1 cytokine interferon γ (IFNγ) and microbial products, and they express high levels of pro-inflammatory cytokines (e.g. TNFα, IL-1, IL-6, IL-12 and IL-23), and inducible nitric oxide synthase (iNOS), and are capable of killing pathogens and tumor cells." (PMID 26799669, 2016).
tumor (continued). "Moreover, the loss of antigen presentation is independent of changes in IFNG within the tumor microenvironment as the sensitivity analysis results suggest that the effect of IFNG is saturated in immunized animals." (PMID 28101055, 2016). "However, strongly radio-responsive tumors demonstrate an increase in intratumoral IFNγ that may likely initiate a strong anti-tumor T cell response." (PMID 27852031, 2016). "Interestingly, the frequency of intratumoral CD4+IFNγ+ T cells significantly correlated with that of intratumoral CD8+IFNγ+ T lymphocytes as well as of intratumoral CD4+IL17+ T cells in both types of tumor, suggesting their coordinated homing to the tumor site." (PMID 26824503, 2016). "It is also indicated that IFNγ could induce the antiproliferative and proapoptotic effects on various tumor cells, repress tumor angiogenesis and produce antitumor cellular responses through activation of natural killer cells, macrophages and CD8+ cytotoxic T cells." (PMID 27342639, 2016). "The discrepancy in PD-L1 staining using different assays including negative results may be due in part to cellular, spatial, and temporal heterogeneity in PD-L1 expression, which is a dynamic marker of response to T cell activation and it is up-regulated on tumor cells by IFNγ." (PMID 27895917, 2016). "Of note, this DLE-derived NK cell population is endowed with properties such as IFNγ production, tumor cell cytotoxicity, and the capability of inducing γδ T lymphocyte proliferation that may, in turn, function as coadjuvant component of innate immune responses against virus-infected or tumor cells." (PMID 27847830, 2016). "Studies demonstrate that while IFNγ is essential for the development and ability of T cells to mount a specific anti-tumor response, it is also essential for the ability of T cells generated in lymphoid organs, including the spleen, to migrate to tumor sites and mount an anti-tumor response." (PMID 27169467, 2016). "Because PD-L1 upregulation is a mechanism of tumoral adaptive resistance, the observed PD-L1 upregulation in the tumor microenvironment following poxvirus-based active immunotherapy treatment is interpreted as the evasion response to activated cytotoxic CD8 T cells producing IFNγ in high amounts." (PMID 26910562, 2016). "However, other studies wherein IFNγ in combination with other agents showed anti-tumor response." (PMID 26390214, 2015). "IFNγ production and cytotoxicity have been considered two distinctive functions of different NK subsets, but growing evidence shows that the main cytotoxic NK subset, CD56dimCD16+ NK cells, that are responsible for mAb-mediated tumor killing, are also able to produce IFNγ following activation." (PMID 26284063, 2015). "The fact that intra-tumoral NK cells are not observed within cancer-associated TLS indicates that tumor-infiltrating NK cells may not influence T-cell response, and are not the cellular source of IFNγ detected within TLS." (PMID 25755654, 2015). "Deletion of AMPK in CD8+ T cells results in decreased production of IFNγ and Granzyme B. Mechanistically, AMPK deficiency in T cells enhances serine/threonine protein phosphatase activity upon activation, thus leading to elevated cell death and impaired anti-tumor functions." (PMID 25760243, 2015). "In settings where the tumour microenvironment alters Th17 function to one that augments tumour development, therapeutic strategies could be considered to harness the cells to a protective phenotype such as inducing the cells to coproduce IFNγ." (PMID 26101460, 2015). "It is evident that inflammatory cytokines and chemokines, for example, tumor necrosis factor-alpha (TNF-α), IL-1 and IL-6, and interferon gamma (IFN-γ), which can be produced by the tumor cells and/or tumor-associated leukocytes and platelets, may add directly to the development of malignancy." (PMID 25814785, 2015).
tumor (continued). "Therefore, it is reasonable to assume that BMSC treatment may reduce proliferation of MDSCs, which in turn maintains the IFNγ+ T cells in tumor-bearing mice." (PMID 25889932, 2015). "It is hypothesized that the immune system, at this stage provides a selection pressure, especially through IFNγ-mediated cytotoxicity, that kills the highly-immunogenic tumor cells but may leave a population of low-immunogenic cells that are more resistant to immune cell-mediated killing." (PMID 26464579, 2015). "However, our finding of a predominantly low IL10 expression combined with high IFNG expression in the highly responsive cluster group B, might be consistent with a high Th1/Th2 balance, a known marker of an appropriate anti-tumor immune response." (PMID 25432519, 2014). "In addition, increases in IFNγ, IL-6, and IL-12 may contribute to the T cell activation and subsequent antitumor response we observed in mice challenged with A20 tumor." (PMID 24454895, 2014). "However, although IFNγ-expressing Th17 lymphocytes mediate potent anti-tumor effects both in human and animals, it will conceivably be challenging to consistently and reproducibly redirect Th17 differentiation towards IFNγ-expressing Th1-like cells following adoptive transfer in vivo." (PMID 24454480, 2013). "Additionally celecoxib influenced interferon gamma that has a pivotal role in tumor suppression." (PMID 23935247, 2013). "However, there is limited understanding regarding the molecular mechanisms of altered methylation, and whether the tumor microenvironment has any effect on DNA methylation and IFNG production." (PMID 24244422, 2013). "Destruction of tumor stroma, a bystander response that may put an advantage to T cells over drugs, may require optimal T cell fitness (as measured by production of IFNγ) and IFNγ-mediated preservation of Fas expression by stromal cells." (PMID 24265631, 2013). "Although IFNγ-mediated inhibition of oHSV replication may be overcome in part by the administration of immunosuppressive drugs such as cyclophosphamide, a drawback to this approach is that it will also inhibit the induction of tumor-specific immunity." (PMID 22924042, 2012). "The reduction in tumor growth and abrogation in tumor cell migration may be explained by an increase in the frequency of activated T and/or NK effector mediated tumor apoptosis and/or T or NK IFNγ mediated anti-angiogenesis." (PMID 22815789, 2012). "Similarly, these same CD4+Foxp3+CD25low Tregs derived from vaccinated Foxp3GFP neu-N mice suppressed high avidity T cell IFNγ secretion in vivo after they were transferred into tumor bearing FVB/N mice treated with the 3T3neuGM vaccine and high avidity T cells." (PMID 22359647, 2012). "The inhibition of tumour-generated CD4+ TReg cells through abolition of cell-to-cell contact was associated with a reduction in the production of IL-10 (69.8±33.6 pg/ml vs 6.3±0.01 pg/ml, n = 3, p = 0.079) and IFNγ (12154±4174 pg/ml vs 0.04±0.01 pg/ml, n = 3, p<0.001)." (PMID 22666318, 2012). "Thus, while the tumor changes the environment in the bladder, as shown by the increase in IFNγ and IL10, it too is changed by the activity of the immune cells recruited to the bladder which selectively destroy the immunogenic cells and thus encourage the survival of less immunogenic cells." (PMID 22013484, 2011). "Thus, for the first time, we directly illustrated a possible link between IFNγ, NSPCs and cellular abnormalities similar to that observed in tumor cells strongly supporting the view that inflammation might be involved in tumor generation via neural stem cells." (PMID 21371330, 2011). "However, it has been identified that some tumor derived Treg cells with the tumor antigen specificity could recognize the autologous antigen specific tumor cell and secret IFNγ in vitro." (PMID 20064222, 2010).